AFP (alpha fetoprotein)
Diseases named in the same sentence as AFP in open-access papers (continued):
Sharing a sentence is not in itself a finding about the gene and the disease.
tumor (continued). "Both nanocomplexes (in the treated HC groups) also suppressed the AFP level (<10 ng/mL compared to >150 ng/mL in the HC untreated group); importantly, DC(I + II) NPs can normalize this tumor marker." (PMID 39076585, 2024). "The expression of MAP3K14 was correlated with Pathologic T stage (p=0.026), Pathologic stage (p=0.032), Tumor status (p=0.024) and AFP (p=0.002)." (PMID 38577603, 2024). "The serum levels of tumor markers, including alpha-fetoprotein (AFP), carcinoembryonic antigen (CEA), and CA 19-9, were within the normal range." (PMID 39640280, 2024). "Tumor markers such as alpha-fetoprotein (AFP) and carcino-embryonic antigen (CEA) are typically normal." (PMID 38473259, 2024). "For instance, Some researchers believe that AFP levels alone are insufficient to predict outcomes, as factors such as tumor size, vascular invasion, and hepatic function play equally significant roles." (PMID 39839797, 2024). "Surprisingly, the tumor had a partial response, and the patient’s serum alpha-fetoprotein returned to normal." (PMID 38728500, 2024). "PARD3 knockout significantly reduced the expression of the tumour marker AFP in the liver, as well as the population of Ki67+ cells." (PMID 38317186, 2024). "The commonly used tumor marker, AFP, has limited sensitivity and specificity, with most patients being diagnosed at a late stage." (PMID 39735192, 2024). "Traditional serum tumor markers (STMs) include alpha fetoprotein (AFP), beta subunit of human chorionic gonadotropin (β-hCG), and lactate dehydrogenase (LDH)." (PMID 39685906, 2024). "The CEUS-predominant model was developed by combining CEUS features and tumor markers (AFP > 400 μg/L and CA 19-9 > 100 U/mL)." (PMID 38353807, 2024). "A policy of biopsying only indeterminate lesions after CT and AFP correlation, especially after multidisciplinary tumor board discussion, would avoid sampling in 93% patients." (PMID 38831055, 2024). "This process integrated protein tumor marker alpha‐fetoprotein (AFP) and cancer genomic hallmarks, copy number aberration (CNA) and fragment size (FS)." (PMID 39704423, 2024). "In such instances, a 3‐month treatment course with an mTOR inhibitor has been shown to improve the outcome of LT for HCC, especially in patients with evidence of high AFP activity within the tumor." (PMID 38250695, 2024). "Angiopoietin-1, among factors implicated in tumor angiogenesis, has been linked to HCC progression and has shown superior performance to AFP in predicting overall survival." (PMID 39286634, 2024). "Clinically, GTS often presents with an increasing abdominal mass or discomfort despite normalization of serum tumor markers like alpha-fetoprotein (AFP)." (PMID 39734342, 2024). "In this cohort, the mean OS of patients with ALBI grade 1 was more than 13 months longer than that of patients with ALBI grades 2 or 3, when they were in the same category divided by tumor number and size and AFP levels." (PMID 38606106, 2024). "The iRGD-induced tumour-to-blood transport of AFP was found to depend on neuropilin-1 and on the concentration gradient between the tumour and the blood, and was primarily seen in animals with small tumours and basally normal blood AFP levels." (PMID 38889481, 2024). "Duvoux’s team proposed a French AFP liver transplantation model consisting of maximum tumor diameter, number of tumors, and AFP level, with transplant eligibility of ≤ 2 points." (PMID 38448905, 2024). "The AUCs of the MODEL 1 by combining CA50, CA19‐9, and AFP were higher than those of the single serum tumor markers." (PMID 38924330, 2024). "Factors such as Child–Pugh class, BCLC class, AFP levels, tumor size, metastasis, and the specific treatment regimen (TACE + Sor + ICI vs. TACE + Sor) were identified as significant predictors of PFS." (PMID 39062006, 2024). "Serum tumor markers (AFP, LDH, or BHCG) at primary diagnosis were increased by 2.5-fold in patients with BGCT (OR=1.8, 95%CI 1.2–2.7, p<0.05)." (PMID 38321336, 2024).
tumor (continued). "Tumor markers including cancer antigen (CA 19-9), alpha-fetoprotein (AFP) and carcinoembryonic antigen (CEA) showed normal values." (PMID 39099991, 2024). "Preoperative tumor markers, including Alpha-Fetoprotein (AFP), Human Chorionic Gonadotropin (HCG), and Lactate Dehydrogenase (LDH), were within normal ranges." (PMID 39013244, 2024). "During that time, CTC burden dropped from 31.8 cells/mL to 11 cells/mL and AFP levels dropped from 978 to 3.5, corresponding to the response of the tumor cells to therapy." (PMID 38727682, 2024). "This transport was tumour-specific and occurred preferentially in animals with small HCCs and low basal AFP levels." (PMID 38889481, 2024). "While most expanded criteria are based on the number and size of tumor nodules, the incorporation of biomarkers as surrogates for biological behavior has gained significant interest, particularly for alpha-fetoprotein (AFP)." (PMID 39272917, 2024). "The initial step of evaluating a testicular mass is done by scrotal ultrasound and obtaining baseline tumor markers (AFP, B-HCG, and LDH)." (PMID 38571873, 2024). "The distribution of OS status, tumor grade, and AFP level were all markedly different between the two subtypes." (PMID 39126216, 2024). "Of note, the expression of pTyr397FAK, N-methyltransferase enzyme (EZH2) and tri-methylation of the H3K27 residue correlated with tumor size and alpha-fetoprotein (AFP) levels." (PMID 38947885, 2024). "Tumor markers, including alpha-fetoprotein (AFP), beta human chorionic gonadotropin (HCG), and lactate dehydrogenase (LDH), were normal." (PMID 39050357, 2024). "In the second step, we focused on the change in tumor markers (ΔAFP and ΔDCP) in patients with high baseline AFP (AFP ≥ 20 ng/mL) and DCP levels (≥ 40 mAU/mL)." (PMID 39321197, 2024). "Model 2 was formulated with the following equation: the sum of the largest tumor size and tumor number + AFP level + ALBI grade." (PMID 38606106, 2024). "Although there have been numerous studies on the combination of AFP and drugs for tumor treatment, the binding mechanism and mode of action of AFP with drugs have scarcely been addressed." (PMID 38678117, 2024). "Laboratory tests showed a slight elevation in alpha-fetoprotein (AFP) levels (AFP: 32.9 ng/ml) while other tumor markers such as carbohydrate antigens 19–9, 125, and 153, and carcinoembryonic antigen were within normal limits." (PMID 39588500, 2024). "Tumor markers such as serum human chorionic gonadotropin (hCG) and alpha fetoprotein (AFP) levels were measured and were found to be normal." (PMID 38281986, 2024). "Serum tumor marker tests revealed an elevated human chorionic gonadotropin (hCG) was 116.9 mIU/mL, alpha-fetoprotein (AFP) was 1.6 ng/mL, and lactate dehydrogenase (LDH) was 219 U/L." (PMID 38394502, 2024). "Recent investigations have elucidated the divergence between AFP-negative and AFP-positive HCC subtypes, providing invaluable insights into the underlying mechanisms driving tumor progression." (PMID 39247201, 2024). "For example, the HCC-related antigen alpha-fetoprotein (AFP) can impair DC function, promoting malignant tumor progression in AFP-positive HCC patients." (PMID 39334927, 2024). "Several other texture features correlated with tumor markers CA‐19‐9 and AFP, as well as with T and N stage of tumors." (PMID 39307946, 2024). "The univariate regression results suggested that TBS, BMI, tumor diameter, tumor number, preoperative AFP content, MVI, BCLC staging, and surgical approach were significantly related to OS (all P < 0.05)." (PMID 39555448, 2024). "We developed two prediction models using the four independent predictive factors for OS: the largest tumor size, tumor number, AFP level, and ALBI grade." (PMID 38606106, 2024). "Potential confounding variables included sex, age, AFP concentration, tumour number, tumour thrombosis, and degree of differentiation." (PMID 38336712, 2024).
tumor (continued). "The ALT (P=0.009), AST (P=0.039), AFP (P=0.003), tumor size (P=0.008), and peritumoral enhancement (P=0.022) showed statistically significant differences between the MVI-positive and MVI-negative groups." (PMID 39184049, 2024). "While identifying the primary tumor, tumor markers indicated elevated alpha-fetoprotein (AFP) and carbohydrate antigen 19-9 (CA 19-9) with normal carcinoembryonic antigen (CEA)." (PMID 39835045, 2024). "In agreement with reduced tumor incidence, serum levels of α-fetoprotein (AFP) were significantly reduced in HKO mice compared with WT mice." (PMID 39190492, 2024). "In this case, there was doubt about the organ of origin of the tumor based on the initial MRI, and also atypical biochemical features, namely high serum LDH and AFP, further contributing to the diagnostic uncertainty." (PMID 38098239, 2024). "In summary, this study sheds light on the role of AFP in promoting tumor progression by stabilizing oncoproteins through its interaction with HSP90." (PMID 39135041, 2024). "The disease burden of the patient is strongly correlated with the serum level of alpha-fetoprotein produced by the tumor, making it a reliable tumor marker." (PMID 38539150, 2024). "Serum AFP levels are recognized as an ideal surrogate biomarker for tumor burden, with higher levels often indicative of more aggressive tumor biology." (PMID 38433845, 2024). "Common tumor markers include AFP, AFU, and DCP, but their sensitivity ranges from 67.7 to 81.7%, with specificities ranging from 70.7 to 90%." (PMID 39310811, 2024). "Second, access to comprehensive information on available treatments, molecular type, tumor markers, such as AFP and CEA, and other relevant data is unattainable due to restricted variables in the SEER database." (PMID 38577906, 2024). "The significantly elevated tumor markers seen in this case, AFP at 19,420 ng/mL and HCG at 4,749 mIU/mL, place the patient in a high-risk category for NSGCTs." (PMID 39697937, 2024). "Tumor marker alpha-fetoprotein (AFP) and cancer antigen (CEA)-125 were within normal limits: 3 ng/mL and 16 Units/mL, respectively." (PMID 39398676, 2024). "TAP detection technology can simultaneously identify multiple tumor markers, such as AFP and CEA, as well as novel markers, enhancing cancer detection accuracy and reducing missed detections in screenings." (PMID 40046668, 2024). "Serum laboratory values such as the tumor index alpha-fetoprotein (AFP), ALT, and AST and clinical variables such as ascites improved after the procedure, but they were not statistically significant (p > 0.05)." (PMID 38610893, 2024). "Tumor size, bilobular invasion, APRI, and AFP level were recognized as independent risk factors for early TACE refractoriness." (PMID 39258671, 2024). "AFP, hepatocirrhosis, tumor diameter, and LMR were discovered to be common influences on the prognosis of patients with HCC and MVI when combined with the results of the intergroup comparison of MVI." (PMID 38284881, 2024). "The positive rate of CK19 was significantly higher in cases with age < 47 years (P = 0.005), tumor diameter > 4 cm (P = 0.016) or AFP ≥ 400 ng/ml (P = 0.007)." (PMID 38332165, 2024). "In particular, Romboutsia strongly correlated with alpha-fetoprotein, an important indicator of HB, suggesting that Romboutsia can be used as a potential microbial marker to distinguish HB tumour tissues." (PMID 39553581, 2024). "Previous recipient selection criteria have been established based on tumor characteristics including tumor number, tumor size, and tumor biology reflected by AFP level, which are closed related to tumor recurrence." (PMID 38408903, 2024). "The pre-transplant AFP (p = 0.001), maximum dominant tumor diameter (p < 0.001), number of tumor nodules (p < 0.001), rate of vascular invasion (p = 0.001), and Ki-67 level (p = 0.044) were higher in patients beyond the Milan criteria." (PMID 39797227, 2024).
tumor (continued). "Serum AFP, an easily accessible biomarker correlated with tumor burden and biology, has an established role in HCC for decades." (PMID 39726604, 2024). "Early detection through imaging and tumor markers like alpha-fetoprotein (AFP) and beta-human chorionic gonadotropin (HCG) is crucial for favorable outcomes." (PMID 39697937, 2024). "Elevated levels of AFP, a fetal hepatocyte-derived protein, are commonly observed and considered as a crucial tumor indicator for monitoring disease progression and response to comprehensive treatment." (PMID 39085725, 2024). "The results demonstrated a significant association between Huaier granules and a reduced risk of recurrence in specific subgroups, including male, age ≥60 years, AFP ≤400 ng/mL, tumor size >2 cm, single tumor, and percutaneous MWA." (PMID 38774215, 2024). "Those criteria include thrombus enhancement, tumor adjacent to the thrombus, venous expansion, neovascularity, and alpha-fetoprotein > 1000 ng/dL." (PMID 38592411, 2024). "In model 2, additional adjustment for number of tumors, tumor size, and alpha-fetoprotein levels similarly found a significantly longer LT waitlist for female patients (β: 15.62; 95% CI, 12.74-18.50)." (PMID 38911272, 2024). "Specifically, this review focused on the effect of AFP on various cells in the TME, tumor immune evasion, and clinical application of AFP in the diagnosis and treatment of HCC." (PMID 38660138, 2024). "A study of independent predictors for MVI identified three variates; tumor diameter, alpha-fetoprotein (AFP) and des-gamma-carboxy prothrombin." (PMID 39336451, 2024). "Compared to previous studies, this study not only found that patients with PVTT benefit more from the triple therapy, but also discovered that patients with larger tumor diameters and higher AFP levels benefit more from the triple therapy." (PMID 39411718, 2024). "Tumor characteristics by imaging, AFP measurement, and histopathology in HCC patients with HBV, ALD, or NAFLD without a history of HCV exposure." (PMID 38230878, 2024). "Our study demonstrated that a combination of clinical factors, including serum AFP level and tumour size, as well as imaging features, including tumour margin and APE, can predict MVI in HCC." (PMID 38281008, 2024). "Due to the tumor morphology in CT imaging and significantly elevated AFP levels in the range of between 1700 and 2212 ng/mL (reference range: ≤8.04 ng/mL), HCC was suspected." (PMID 39064538, 2024). "The traditional serum tumor markers (STMs) used in the diagnosis of TGCTs are α-fetoprotein (AFP), Beta human chorionic gonadotropin (β-hCG), and lactate dehydrogenase (LDH)." (PMID 38611057, 2024). "Serum tumor markers, including alpha-fetoprotein (AFP), human chorionic gonadotropin (HCG), and lactate dehydrogenase (LDH), were within normal limits." (PMID 39372378, 2024). "According to TCGA (LIHC-TCGA), ING5 mRNA expression was positively correlated with tumor status, a high level of serum alpha-fetoprotein (AFP) (>400 ng/ml), vascular invasion, and histologic grade." (PMID 39247819, 2024). "Tumor markers were within normal ranges, with alpha-fetoprotein (AFP) at 11.6 ng/mL and protein induced by vitamin K absence or antagonist-II (PIVKA-II) at 35 AU/mL." (PMID 39463668, 2024). "Ramucirumab, the only drug that has to be guided by a biomarker, has been approved for patients with tumor progression on sorafenib and an alpha fetoprotein (AFP) value of at least 400 ng/mL." (PMID 38672997, 2024). "In the multivariant analysis using Cox regression, a model using ECOG status, PVTT, tumor volume, and AFP for PFS and OS was conducted based on the univariate analysis; the C‐index for the model was 0.72 and 0.75, respectively." (PMID 38689147, 2024). "These four SNRGs exhibited notable correlations with key clinical parameters, including tumor size, AFP level, microvascular invasion (MVI), ECOG score, and tumor grade." (PMID 38972883, 2024).
tumor (continued). "LRB1 (Light response BTB1): Increased LRB1 shows a significant association with the risk of HCC as its levels are positively correlated with the expression of AFP, tumor stage advancement, venous invasion, and poor recurrence-free survival rates." (PMID 39448589, 2024). "His blood investigations showed normal tumor marker levels including alpha-fetoprotein (AFP), human chorionic gonadotropin (beta hCG) and carcinoembryogenic antigen (CEA)." (PMID 39574987, 2024). "AFP, recognized as the most widely used tumor biomarker for HCC, plays a crucial role in the progression of HCC." (PMID 38773511, 2024). "Conventional clinical laboratory indicators, including tumor markers such as AFP, were all excluded in the univariate analysis due to their relatively poor correlation compared to other variables." (PMID 39055557, 2024). "It incorporates both static factors (such as tumour size and number) and biological markers (like alpha-fetoprotein (AFP) levels)." (PMID 39519230, 2024). "The HAP score also incorporates four variables related to tumors: alpha-fetoprotein, tumor size, serum albumin, and total bilirubin." (PMID 38589828, 2024). "MVI was found to be substantially linked with four subgroups of HCC patients with hepatocirrhosis, positive AFP, tumor diameter >50 mm, and LMR ≤3.4, and the prognosis of MVI‐positive patients in all four subgroups tended to be worse." (PMID 38284881, 2024). "Previous cases have involved laboratory tests for tumor markers like alpha-fetoprotein (AFP), beta human chorionic gonadotropin (bHCG), and lactate dehydrogenase (LDH)." (PMID 39013244, 2024). "AFP-TCR-T expressing a novel engineered IL-21R with constitutive IL-21 signal showed increased proliferation and tumor-infiltrating capacity, resistance to antigen-induced cell death, and superior antitumor function compared with conventional AFP-TCR-T." (PMID 38643203, 2024). "The model analyzed factors such as the size of the tumor, the patient's age, the level of AFP in the blood, and the prothrombin time to make predictions." (PMID 39367397, 2024). "AFP expression and secretion of HCC were positively associated with tumor characteristics (tumor burden, aggressiveness, worse tumor differentiation) and negatively correlated with treatment response." (PMID 39867887, 2024). "Clinicopathological characterization indicated that PKM2 or ITGA3 overexpression was associated with age, serum AFP, TNM stage, BCLC stage, tumor number, tumor size, and microvascular invasion." (PMID 39070142, 2024). "In the context of HCC, studies have demonstrated that AFP plays a significant role in tumor progression by suppressing immune system activity and inhibiting T cell proliferation." (PMID 39335733, 2024). "Patients with elevated blood tumor markers (AFP and CA19‐9) often exhibited positive results in IHC." (PMID 39162366, 2024). "AFP and its downstream pathways play a key role in this system, making them targets for novel tumor treatment." (PMID 38660138, 2024). "The HPCL group had a significant increase in ALP, ALT, AST, GGT, T. Bilirubin, D. Bilirubin, and Albumin, in addition to the lipid profile (TC, TG, HDL-C, and LDL-C) and the AFP, the tumor marker, in comparison to the control group (p < 0.05)." (PMID 39479501, 2024). "Maximum tumor diameter ≥ 10 cm (P = 0.005), portal vein invasion (P = 0.032), extrahepatic disease (P = 0.011), AFP ≥ 200 ng/mL (P = 0.024), and abnormal ALP (P = 0.035) were associated with worse PFS." (PMID 38976071, 2024). "The studied tumor markers, namely, CA15-3, CEA, CA125, and AFP, have different physiological origins, and each becomes a marker for cancer due to its overexpression or aberrant presence in the context of tumor growth." (PMID 38672729, 2024). "OS and PFS were significantly improved in patients who received TLT compared to those who received TL, patients with a largest tumor diameter greater than 7 cm, AFP > 400 ng/ml, Child-Pugh class A and PVTT appeared to derive more benefit." (PMID 39411718, 2024).